SMAD2 (SMAD family member 2)
Diseases named in the same sentence as SMAD2 in open-access papers (continued):
Sharing a sentence is not in itself a finding about the gene and the disease.
infection (continued). "Notably, based on the analysis of the data, we hypothesize that up-regulated TGFβ1, involved with induction of fibrosis during infection, may work through SMAD2/3/4 signaling." (PMID 27661612, 2016). "However, the mRNA levels of SMAD2 remained unchanged during the course of infection (p>0.05)." (PMID 18776948, 2008). "Two of the main SMAD pathway elements, SMAD2 and SMAD4 are less robustly regulated during infection, with SMAD2 showing minor upregulation at L timepoints." (PMID 39863683, 2025). "GADD45b expression was concomitantly upregulated throughout infection but was markedly suppressed by SB431542 treatment, suggesting that SB431542 inhibits apoptosis via suppression of canonical Smad2/3 signaling and GADD45b expression." (PMID 40879372, 2025). "Kidneys of TC‐treated mice exhibited a higher Smad2:Smad3 ratio than vehicle‐treated mice, beginning before the onset of UTI and continuing throughout the course of infection." (PMID 32227630, 2020). "Cells were infected with 200 genome equivalents per cell and complete infection was confirmed by monitoring GFP expression, and subsequently, lysates and total RNA was collected for Western blot and RT-qPCR to monitor SMAD2 expression." (PMID 26545119, 2015). "Levels of mRNA for TGF-β isoforms 1, 2, and 3 as well as for SMAD2 and SMAD3 were measured by reverse transcription polymerase chain reaction (RT–PCR) at 0 h, 4 h, 8 h, 12 h, and 24 h after infection." (PMID 18776948, 2008). "Critically, targets of transcription factors known to regulate inflammation (IRF1, STAT1, STAT3) and fibrosis (SMAD2/3, EGR1, TEAD4, YAP1) appeared to be highly induced in the host, consistent with prior reports of infection-dependent induction of pro-inflammatory and pro-fibrotic gene expression." (PMID 36923592, 2023). "Gene expression analysis showed that Smad2 is significantly down-regulated while Smad1 and the activin receptor gene Acvr1b are up-regulated in the resistant BALB/c mouse during infection, but not in the susceptible CBA/Ca." (PMID 24594938, 2014). "The R-SMADs Smad2 and Smad3, which, upon phosphorylation, interact with Co-SMAD and translocate to the nucleus, were identified as key proteins in primary and secondary infection." (PMID 25341656, 2014). "In the ileal network, JAK2 and CREB1, as well as SMAD2, SMAD3 and ERK2 (MAPK1) seem to play a central role in the intracellular PPI signalling driven by viral miRNAs and viral proteins, respectively, and JAK2 and both SMAD2 and SMAD3 were also upregulated upon infection." (PMID 35501398, 2022). "The results suggested that targeting the miRNA-34a-5p/SMAD2 axis might be a new therapeutic strategy in treatment of bone nonunion after anti-infection treatment in infected bone nonunion." (PMID 36694425, 2022). "However, infection with either ΔvFLIP or ΔvCyc mutant viruses did not restore SMAD2 expression in TIVE cells suggesting differences by which both proteins contribute to the up-regulation of the miR-17-92 cluster between both cell types." (PMID 26545119, 2015). "No noticeable changes were found as a result of infection with respect to levels of TGF-β2, TGF-β3, and SMAD2 in HCE cells." (PMID 18776948, 2008). "Interestingly, Smad2 located near to the QTL on chromosome 18 was differentially regulated in BALB/cOlaHsd, but not in CBA/CaOlaHsd, during the infection." (PMID 24594938, 2014).
adenocarcinoma (7 papers, 2013 to 2023). A common cancer characterized by the presence of malignant glandular cells. "On the contrary, Smad2 transcript and protein, as well as phosphorylation of SMAD3 and SMAD, remained unchanged in OPN−/−TRAMP NE tumors versus TRAMP adenocarcinomas." (PMID 26700622, 2016). "In the present study, using ALK5 small molecule inhibition and siRNA knockdown of Smad2 and Smad3, we demonstrate that the upregulation of PAR-1 expression is both ALK-5 and Smad3-dependent in A549 adenocarcinoma cells." (PMID 27566553, 2016). "As protein levels of TGFbRI and TGFbRII were comparable between OPN−/−TRAMP NE tumors and TRAMP adenocarcinoma (not shown), we focused on proteins downstream the TGFβ pathway, particularly Smad2 and Smad3, which are crucial mediators of TGFβ activity in PCa." (PMID 26700622, 2016).
vasculopathy (4 papers, 2014 to 2024). "In vitro studies demonstrated that the underlying mechanisms of FIR therapy inhibiting OAT vasculopathy may be associated with the inhibition of the Smad2-Slug axis endothelial mesenchymal transition (EndoMT)." (PMID 35625826, 2022). "The close correlation of vascular TGF-β-induced SMAD2/3 phosphorylation and the severity of vasculopathy is supported by recent genome wide association, and systems biology studies identified the TGF-β–SMAD pathway to be strongly associated with coronary artery disease." (PMID 30700974, 2018). "The incidence of OAT vasculopathy was reduced by reducing TGF-β-induced EndoMT via the Smad2-Slug-axis signaling pathway." (PMID 35625826, 2022). "Furthermore, in the PD parietal arterioles, C1q and terminal complement complex abundance correlated with the level of dialytic glucose exposure, the abundance of phosphorylated SMAD2/3, and the degree of vasculopathy." (PMID 30700974, 2018).
bacterial infection (3 papers, 2012 to 2024). "Our most confident prediction for miR-148a is a SMAD2 gene involved in regulation of cell growth and proliferation - two processes which are rather silenced during stressful bacterial infection." (PMID 22953717, 2012). "Upon bacterial infection, tilapia T cells produce TGF-β1, which in turn initiates TGF-βR/Smad signaling pathway and results in the nuclear translocation of Smad2/3." (PMID 36581209, 2022). "SPY1 vaccination activated Foxp3, increasing the frequency of CD4+CD25+Foxp3+ Tregs during vaccination; SPY1 elevated Smad2/3 and phosphor-Smad2/3 downregulated a negative signal by Smad7 during live bacterial infection (Smad 1–9 regulate TGF-β receptor signaling)." (PMID 39340024, 2024).
cardiovascular disease (3 papers, 2013 to 2024). "In cardiovascular disease, much evidence demonstrates that GDF15 is a protective cytokine against multiple stimuli via many signaling pathways including PI3K/Akt, ERK1/2, and SMAD2/3." (PMID 23799024, 2013). "In cardiovascular disease, GDF15 has great potential as a biomarker for prognosis and as a protective cytokine against different stimuli via specific signaling pathways, such as PI3K/Akt, ERK1/2, and SMAD2/3." (PMID 23799024, 2013).
colorectal (3 papers, 2017 to 2023). "The Smad2 and Smad3 are major downstream regulators that promote the TGF-β1-mediated lung fibrosis." (PMID 37580529, 2023).
inflammation (3 papers, 2020 to 2024). Aberrant reaction of the microcirculation characterized by movement of fluid and leukocytes from the blood into extravascular tissues. "THBS1 can regulate inflammatory cytokine secretion and angiogenesis by activating NF-κB, and CTRP9 attenuates atrial inflammation and fibrosis by suppressing the NF-κB and Smad2/3 signaling pathways." (PMID 33414684, 2020).
Neurological Disease (3 papers, 2023 to 2024). "On the other side, cotreatment with WSLE and WSLE NE revealed a signification downregulation of APP, GFAP, vimentin, TGF-β, Smad2, and BAX target genes which coincided with previous studies which highlighted the neuroprotective effect of WSLE in a variety of neurological disorders." (PMID 38630361, 2024).
neurodegenerative disease (2 papers, 2018 to 2023). A disorder of the central nervous system characterized by gradual and progressive loss of neural tissue and neurologic function. "In some neurodegenerative diseases, TGF-β1 stimulates the production of inflammatory cytokines such as IL-1β and TNF-via phosphorylation of Smad proteins, including Smad2 and Smad3, in rat neurons." (PMID 37240885, 2023).
hematologic malignancies (1 paper, 2025). "The activation of these pathways downstream of TGF-β, converging on Smad2/3 and ERK1/2, further supports that AML-derived exosomes induce EMT-like features despite the absence of classical EMT in hematologic malignancies." (PMID 41020812, 2025).
infectious disease (1 paper, 2019). A disorder directly resulting from the presence and activity of a microbial, viral, or parasitic agent in humans. "The analysis in CD34+ cells highlighted mechanisms related to SUMOylation of chromatin organization proteins, infectious disease, transcriptional activity of SMAD2/SMAD3 and cellular responses to stress." (PMID 31546608, 2019).
SMAD2 also shares sentences with these, for which no sentence is quoted: pancreatic ductal adenocarcinoma (7 papers); autoimmune disease (6); hypertrophy (4); myelodysplastic syndrome (4); gastrointestinal tumors (3); multiple myeloma (3); renal carcinoma (3); acute myocardial infarction (2); amyloid (2); anaplastic thyroid cancer (2); Benign Prostate Hyperplasia (2); cardiac arrhythmia (2); clear cell renal cell carcinoma (2); congestive heart failure (2); hypertensive nephropathy (2); metabolic disorders (2); metastasis (2); steatosis (2); viral myocarditis (2); abdominal aortic aneurysm (1); acute lung injury (1); acute megakaryoblastic leukemia (1); acute myeloid leukemia (1); acute respiratory distress syndrome (1); airway hyperresponsiveness (1); American trypanosomiasis (1); aortic valve disease (1); aortic valve stenosis (1); appendiceal adenocarcinomas (1); arteriopathies (1).
A further 99 diseases each share a sentence with SMAD2 in 1 paper.